TNF (tumor necrosis factor)
Diseases named in the same sentence as TNF in open-access papers (continued):
Sharing a sentence is not in itself a finding about the gene and the disease.
juvenile idiopathic arthritis (continued). "A similar subpopulation of γδ T cells was found to be increased in synovial fluid and blood of patients with juvenile idiopathic arthritis, which expressed IFN-γ and TNF-α to the same degree as CD4+ T cells." (PMID 38743491, 2024). "Therefore, we explored changes in the faecal bacteriome and metabolome upon anti-TNF administration [and therapeutic response] in children with CD and contrasted those to anti-TNF-treated children with juvenile idiopathic arthritis [JIA]." (PMID 37527838, 2024). "We describe the first paediatric case of a patient affected by cystic fibrosis, Basedow's disease and juvenile idiopathic arthritis who was contemporarily treated with elexacaftor/tezacaftor/ivacaftor (ELX/TEZ/IVA) and anti-tumor necrosis factor α (anti-TNFα)." (PMID 36902517, 2023). "A recent study analyzed the relationship between serum S100A8/S100A9 and S100A12 and the maintenance of clinical inactive disease (CID) in patients with polyarticular forms of juvenile idiopathic arthritis (PF-JIA) while on anti-TNF- therapy and disease flare following withdrawal of treatment." (PMID 30828327, 2019). "The first clues for a link between anti-TNF therapy and increased type-I IFN expression came from the observation that anti-TNF therapy induces an IFN signature in blood of juvenile arthritis patients." (PMID 30555460, 2018). "Etanercept (ETN), a tumor necrosis factor (TNF) antagonist, has been the first biologic agent registered for use in children with juvenile idiopathic arthritis (JIA)." (PMID 27993144, 2016). "Malignancy risk may be increased in chronic inflammatory conditions that are mediated by tumor necrosis factor (TNF), such as juvenile idiopathic arthritis (JIA), but the role of TNF in human cancer biology is unclear." (PMID 24225257, 2013). "Local blockage of TNF-α may be an alternative treatment approach against TMJ involvement in juvenile idiopathic arthritis (JIA)." (PMID 19200378, 2009). "In juvenile idiopathic arthritis (JIA), it is unclear whether this relates to differential changes following one of the most common treatments, TNF-inhibitors (TNFi)." (PMID 42320045, 2026). "Tofacitinib has been approved by the US FDA for the treatment of active polyarticular juvenile idiopathic arthritis (JIA) in children aged 2 years and older, particularly for patients who have shown inadequate response or intolerance to one or more TNF inhibitors." (PMID 41321444, 2025). "Hurych and colleagues compared TNF inhibitors in CD and juvenile idiopathic arthritis (JIA) and found no changes in the fecal microbiome or metabolome for the JIA population, in contrast to the CD patients." (PMID 38666993, 2024). "Nevertheless, recent data showed that booster MMR vaccine in patients with juvenile idiopathic arthritis receiving bDMARDs (anti-TNFα, anti-IL-1, or anti-IL-6) is safe and immunogenic, with no patients developing a disease flare." (PMID 37439850, 2023). "The cytokine TNF-α, beyond its well-known proinflammatory activity is involved in this process and this is one of the reasons why the TNF-α inhibitors are widely used in the treatment of juvenile idiopathic arthritis patients." (PMID 30930898, 2019). "Even in this age of targeted biologic therapies such as tumor necrosis factor-α inhibitors, nonsteroidal anti-inflammatory drugs (NSAIDs) are integral to the treatment of juvenile idiopathic arthritis (JIA)." (PMID 25057265, 2014). "Blockage of TNF-α has already proven its efficacy in children with juvenile idiopathic arthritis not responding to standard therapy." (PMID 19200377, 2009). "Iglesias E, Torrente-Segarra V, Bou R, Ricart S, González MI, Sánchez J, Calzada J, Antón J. Non-systemic juvenile idiopathic arthritis outcome after reaching clinical remission with anti-TNF-α therapy: a clinical practice observational study of patients who discontinued treatment." (PMID 37848930, 2023).
juvenile idiopathic arthritis (continued). "It binds to and neutralizes soluble TNF-α and TNF-β (lymphotoxin) and is approved for the treatment of RA, juvenile idiopathic arthritis (JIA), PsA, axial spondyloarthritis and PP." (PMID 30643992, 2019). "Abatacept has also demonstrated efficacy in patients with juvenile idiopathic arthritis (JIA) who have not responded to traditional DMARDs or TNF blockers." (PMID 22997525, 2012). "There are no clear differences in the survival of the second TNF antagonist among patients with different diagnosis, although there seems to be a trend toward worse survival in the second trial of a TNF antagonist in RA, and even more in juvenile idiopathic arthritis." (PMID 16507128, 2006). "There is a very high expression of certain proinflammatory cytokines, such as tumour necrosis factor α (TNFα), which is why the use of cytokine blocking drugs is used to treat many of these IMIDs (IBD, uveitis, psoriasis, PAs, and juvenile idiopathic arthritis/JIA)." (PMID 36101354, 2022). "Patients with diverse AID such as psoriasis (Pso), psoriatic arthritis (PsA), RA, Crohn's disease (CD), ulcerative colitis (UC), ankylosing spondylitis (AS), juvenile idiopathic arthritis (JIA), but not MS, have benefitted from TNF-α inhibition." (PMID 32296421, 2020).
myeloma (187 papers, 2003 to 2026). "TNF-alpha, a proinflammatory cytokine with a central role in bone pathophysiology, is associated with cell growth, death, and differentiation in multiple myeloma." (PMID 39329904, 2024). "The addition of recombinant TNF‐α to mature BMAd cultures for 72 hours also caused a reduction in Oil Red O staining, indicating a decrease in BMAd number in a similar manner to myeloma/BMAd co‐culture." (PMID 31886918, 2020). "Elevated levels of TNF‐α have long been associated with myeloma, and our results provide new insights into the mechanisms by which this key inflammatory cytokine promotes myeloma disease progression." (PMID 31886918, 2020). "Activation of canonical NFκB signaling in myeloma cells by tumor microenvironment derived TNF has been implicated in environmental drug resistance." (PMID 27641334, 2017). "In sum, we provide evidence that cancer-associated mutations perpetuate TNF-induced pro-survival NFκB activity through autoregulatory RelB control and thereby exacerbate environmental drug resistance in multiple myeloma." (PMID 27641334, 2017). "In sum, we provide evidence that cancer-associated mutations perpetuate TNF-induced pro-survival NFκB response through autoregulatory RelB control and thereby exacerbate environmental drug resistance in multiple myeloma." (PMID 27641334, 2017). "TNFα, as a proinflammatory cytokine, is associated with various processes for multiple myeloma progression such as cell growth, death, and differentiation." (PMID 24151609, 2013). "Bcl-3 was induced in myeloma cell lines by interleukin (IL)-6, IL-21, IL-15, tumor necrosis factor-α and IGF-1, and its upregulation was associated with increased proliferation of the cells." (PMID 19191868, 2009). "An association between malignancy and TNF polymorphisms includes non-Hodgkin's lymphoma and myeloma." (PMID 12966432, 2003). "Moreover, the dissemination of myeloma is associated with the production of IL-6 and tumor necrosis factor-alpha (TNF-α)." (PMID 38961036, 2024). "Moreover, tumor necrosis factor-alpha is instrumental in osteoclastogenesis, which leads to bone resorption and is linked to the development of bone lesions in multiple myeloma patients." (PMID 39329904, 2024). "In MM patients, however, a high level of IFNG has been shown to be independently correlated with patient survival;59 increased frequency of IFN‐γ+TNF+ CD8+ BM T cells was associated with the profound immune‐driven control of myeloma in a BM transplantation model." (PMID 34845849, 2021). "Moreover, the addition of recombinant TNF‐α also caused a change in BMAd number in a similar manner to myeloma/BMAds co‐cultures." (PMID 31886918, 2020). "While TNFα signaling itself causes a modest increase in proliferation, it induces expression of adhesion molecules resulting in a 2–4 fold increase in binding of myeloma cells to BMSC." (PMID 33634031, 2020). "Finally, brief TNF stimulation elicited late-acting expressions of NF-κB target pro-survival genes in p100-deficient myeloma cells." (PMID 31134075, 2019). "In view of the anti-inflammatory properties of APN, decreased APN levels in myeloma malignancy are hypothesized to be associated with increased IL-6 and tumor necrosis factor alpha (TNF-α)production." (PMID 23691481, 2012). "In contrast, multiple myeloma that is associated with osteolytic bone disease due to excessive osteoclast formation and activity has high levels of circulating pathological inflammatory cytokine TNFα in the patient blood as well as SELENOW in osteoclast progenitors and mature osteoclasts." (PMID 38683225, 2024). "Exogenously added TNF or cell-free supernatant from proteasomal inhibitor-treated immune or multiple myeloma cells combined with TNF, further compromises the cellular integrity of HPMECs when compared to drug alone conditions." (PMID 42253955, 2026). "It has been found that some patients with multiple myeloma had significantly elevated levels of TNF-α during CRS after BCMA CAR T cell infusion." (PMID 40536724, 2025).
myeloma (continued). "Mechanistically, the combination of L19-TNFα and L19-IL2 eradicated tumors in J558L myeloma BALB/c mice likely via TNFα-induced tumor necrosis and L19-TNFα/L19-IL2-mediated local cellular immune reactions." (PMID 41568361, 2025). "The small molecule XRK3F2, which specifically targets p62 ZZ-domain, was shown to impair TNFα-induced NFκB phosphorylation in bone marrow stromal cells from multiple myeloma patients." (PMID 41326849, 2025). "TNF-α then induces myeloma cells to enter the cell cycle and supports the sustained growth of malignant plasma cell lines." (PMID 41300981, 2025). "Within the bone marrow microenvironment, adipocyte-derived IL-6 and TNFα enhance EZH2 expression in myeloma cells." (PMID 40756901, 2025). "Next, we measured the levels of M-CSF and RANKL, which mediate normal osteoclast differentiation, and those of pathological osteoclastogenic inflammatory IL1β and TNFα in the serum obtained from patients with multiple myeloma using ELISA." (PMID 38683225, 2024). "TNF-alpha can stimulate IL-6 secretion by osteoblasts and stromal cells and accumulated IL-6 stimulates the growth of multiple myeloma cells." (PMID 39329904, 2024). "It has also been shown that TNF-α promotes the growth of myeloma cells and contributes to myeloma bone disease, both directly and through the activation of interleukin 6 (IL-6)." (PMID 39830670, 2024). "Our findings suggest a possibility that feedforward signaling of osteoclastogenic SELENOW by TNFα derived from multiple myeloma induces overactive osteoclast differentiation, leading to bone loss during multiple myeloma." (PMID 38683225, 2024). "Malignant myeloma cells secrete several cytokines, such as tumor necrosis factor, interleukin-3, receptor activation of NFκB ligand, and macrophage inflammatory protein-1α, which increase osteoclaster-mediated bone destruction." (PMID 37109052, 2023). "TNF-α is a pleiotropic cytokine that mediates inflammatory responses and induces myeloma cells to produce high IL-6 levels." (PMID 37250588, 2023). "TNF-α has been shown to not only affect the vessel wall permeability but also directly enhances trans-endothelial myeloma cell migration." (PMID 37744361, 2023). "They found the ability of myeloma cells to downregulate adiponectin was dependent in part on TNF-α which was significantly correlated with tumor burden in the BM plasma of myeloma-bearing mice." (PMID 36909335, 2023). "Conversely, the addition of a neutralizing antibody to TNF-α in myeloma/BMAd co-cultures blocked the suppression of adiponectin and prevented the reduction in BMAd number." (PMID 36909335, 2023). "The authors further investigated the intercellular crosstalk between MSC and immune or myeloma cells, and they found that TNF and IL-1β were mainly expressed by cytotoxic T cells, NK cells and monocytes respectively." (PMID 37259170, 2023). "In a second clinical trial of opaganib 58% of patients with refractory multiple myeloma achieved stable disease or better, and patients had decreased plasma levels of TNFα, EGF and VEGF." (PMID 38069222, 2023). "S100A9 induced MDSC to express and secrete inflammatory and pro-multiple myeloma cytokines, including TNFα, IL6, and IL10." (PMID 36923707, 2023). "Thalidomide has been shown to inhibit tumor angiogenesis and dampen inflammation thus counteracting the release of cytokines such as TNF-α that are essential for myeloma cell growth." (PMID 37744361, 2023). "Its use in multiple myeloma was attributed to the immunomodulatory and anti-angiogenic activity which downregulates the expression of TNF-α and IL-6 by the stromal cells in the bone marrow, thereby inhibiting the proliferation of multiple myeloma cells." (PMID 36966238, 2023). "PG2 is characterized by high monocyte and T cell infiltration into the myeloma niche coinciding with high levels of pro-inflammatory cytokines TNF-α and IL-6." (PMID 37081258, 2023).
myeloma (continued). "The study is aimed at analyzing the predictive value of serum Ig A, Ig G, and TNF-α in the recurrence of multiple myeloma (MM)." (PMID 36277989, 2022). "Curcumin has an efficacy in improving overall remission and decreasing NF-κB, VEGF, TNF-α, and IL-6 levels in myeloma patients." (PMID 35919637, 2022). "➢Inhibits IκB kinase β (IKKβ, IC50 = 8.5 nM ) and IKKα (IC50 = 250 nM).➢Reduces the constitutive phosphorylation of IκBα and NF-κB p65 in myeloma cells at 50 μM. ➢Prevents HIV-1 reactivation induced by TNF-α in HIV latently infected cells (IC50 = 0.56 μM)." (PMID 36146786, 2022). "﻿This study revealed that curcumin affects in decreasing NF-κB level after 4 cycles of treatment and the remission of myeloma patient has a correlation with TNF- levels." (PMID 35919637, 2022). "These published inconsistences in regards the effects of TNF on myeloma progression or inhibition prompted us to investigate the therapeutic effects of this cytokine in the context of oncolytic virotherapy with MYXV." (PMID 35251496, 2022). "In serum of 57 patients, we found that IL-4, IL-6, IFN-γ, and TNF-α significantly increased in multiple myeloma compared with healthy control, especially IL-6 and IFN-γ." (PMID 35342422, 2022). "For example, miR-21 is induced by tumor necrosis factor-α (TNF-α) in endothelial cells, by interleukin-1β (IL-1β) in chondrocytes and by interleukin-6 (IL-6) in myeloma cells." (PMID 34222229, 2021). "Progression of MM at early onset is driven by abnormally low levels of apoptosis, a high mitotic rate, and increased transendothelial migration of myeloma cells, partially mediated by TNF through NF-κB activation." (PMID 33917839, 2021). "The Edwards laboratory recently built on their previous findings by demonstrating that myeloma cells downregulate the anti-myeloma protein adiponectin via TNFα." (PMID 33498240, 2021). "Other drugs, such as lenalidomide and dexamethasone, which exhibit anti-TNFα properties, have also been given successfully with bortezomib for the treatment of multiple myeloma." (PMID 35126148, 2021). "In clinical practice, we found some patients with multiple myeloma developed markedly increased levels of tumor necrosis factor (TNF)- α during the CRS period after anti-BCMA CAR T cell infusion." (PMID 33608054, 2021). "It was shown that myeloma-cell-derived TNF downregulates adiponectin in bone marrow adipocytes, altering the bone microenvironment to support disease progression." (PMID 33917839, 2021). "The authors confirmed the ability of S100A9 to induce the secretion by myeloid-derived suppressor cell (MDSCs) of inflammatory and pro-myeloma cytokines including TNFα, IL-6, and IL-10." (PMID 34445745, 2021). "In early myeloma disease, the interaction of myeloma cells with the bone marrow microenvironment initiates the production of IL-1 and TNF-α." (PMID 34201396, 2021). "Bortezomib was also shown to inhibit NF-κB activation in multiple myeloma (MM) cells via inhibition of tumor necrosis factor alpha (TNF-α)." (PMID 34203106, 2021). "BM adipocytes secrete several adipokines and growth factors (e.g., MCP-1, SDF-1α, leptin, TNFα, insulin, resistin) which recruit myeloma cells and promote myeloma growth and protection from chemotherapy." (PMID 34067236, 2021). "More importantly, we show that myeloma cells are able to manipulate their environment by downregulating adiponectin in these BMAds, at least in part via the secretion of TNF‐α." (PMID 31886918, 2020). "By demonstrating how TNF‐α downregulates BMAd‐derived adiponectin, we reveal a new mechanism by which myeloma cells alter the bone microenvironment to support disease progression." (PMID 31886918, 2020). "Another member of the TNF family involved in myeloma growth and survival in the bone marrow microenvironment is TNFα." (PMID 33634031, 2020). "TNF-α independently promoted the proliferation of myeloma cells, and induced the expression of CCL2 in myeloma cells together with IL-6." (PMID 31334678, 2019).